LNX2 (ligand of numb-protein X 2)
Synonyms: PDZRN1; MGC46315
Tractability: Antibody: its Gene Ontology location is reachable by antibodies, with medium confidence; the Human Protein Atlas places it where antibodies can reach. PROTAC: ubiquitination databases record sites on it.
Gene: Protein-coding gene on chromosome 13 (27,545,911 to 27,621,344, reverse strand). Ensembl gene ENSG00000139517.
Subcellular location (Human Protein Atlas): Vesicles; Cytosol; Plasma membrane
Gene Ontology:
Molecular function: identical protein binding; protein binding; ubiquitin-protein transferase activity; PDZ domain binding
Cellular component: plasma membrane
Genetic constraint (gnomAD): Loss-of-function variants: 33 observed, 63.92 expected, observed/expected ratio (o/e) 0.52, 90% interval 0.39 to 0.69. The upper end of that interval is the gene's LOEUF score, 0.69, which puts it in group 2 of 6, group 1 being the genes least tolerant of losing a copy. Missense variants: 765 observed, 859.67 expected, observed/expected ratio (o/e) 0.89, 90% interval 0.84 to 0.94. Synonymous variants: 322 observed, 322.56 expected, observed/expected ratio (o/e) 1, 90% interval 0.91 to 1.1.
Homologues: Orthologues: chimpanzee LNX2 (99% identical), macaque LNX2 (98% identical), rabbit LNX2 (92% identical), guinea pig LNX2 (92% identical), dog LNX2 (91% identical), mouse Lnx2 (90% identical), rat Lnx2 (88% identical), pig LNX2 (87% identical), tropical clawed frog lnx2 (80% identical), zebrafish lnx2a (67% identical), Caenorhabditis elegans frm-5.1 (10% identical), Caenorhabditis elegans frm-5.2 (10% identical). Paralogues in human: LNX1 (50% identical), PATJ (29% identical), MPDZ (27% identical), FRMPD2 (17% identical), STXBP4 (10% identical).
Diseases named in the same sentence as LNX2 in open-access papers:
LNX2 is named in the same sentence as 16 diseases in open-access papers, as found by Europe PMC text mining. Sharing a sentence is not in itself a finding about the gene and the disease. The quoted sentences say what the papers report.
Anxiety (4 papers, 2017 to 2025). Intense feelings of nervousness, tension, or panic often arise in response to interpersonal stresses. "Here, building upon these previous studies, we performed a detailed analysis of stress, anxiety, risk taking and ultrasonic vocalisations in Lnx1-/- and Lnx2-/- single and double knockout animals of both sexes." (PMID 40269869, 2025). "Overall, these observations pinpoint the specific roles of LNX1 and LNX2 proteins in modulating certain aspects of anxiety and risk-taking behaviour and social communication in mice." (PMID 40269869, 2025). "In summary, the analysis presented here delineates for the first time distinct roles for LNX1 and LNX2 proteins in regulating anxiety-related and risk-taking behaviour, ultrasonic vocalizations and body weight." (PMID 40269869, 2025). "This suggests that the influence of LNX2 on anxiety and risk-taking behaviours is likely to be caused by subtle neural circuit defects established in the forebrain during development that then persist into adulthood." (PMID 40269869, 2025). "Overall, the results of the dark-light emergence and wire beam bridge tests clearly demonstrate decreased anxiety-related or increased risk-taking behaviour in Lnx1−/−;Lnx2−/− mice and suggest a more prominent involvement of Lnx2 versus Lnx1 knockout in causing this phenotype." (PMID 40269869, 2025). "Here we significantly extend this work by examining anxiety-related and risk-taking behaviours in Lnx1-/- and Lnx2-/- single knockout animals for the first time and by analysing previously unexplored aspects of behaviour in both single and double knockout animals." (PMID 40269869, 2025). "Decreased anxiety-like or increased risk taking in the dark-light emergence test and wire beam bridge tests was observed for both double knockout and Lnx2 single knockout animals, suggesting a more prominent role for LNX2 in these behavioural paradigms." (PMID 40269869, 2025). "The main behavioural alteration observed in these Lnx1-/-;Lnx2-/- double knockout animals was decreased anxiety-related behavior in the open field and elevated plus maze paradigms." (PMID 40269869, 2025). "This argues against increased novelty seeking, however the exact nature of the decreased anxiety-related phenotype seen in Lnx2−/− and Lnx1−/−;Lnx2−/− requires further careful analysis." (PMID 40269869, 2025). "The most notable findings were decreased anxiety-related behaviour in the elevated plus maze for both males and females, and in the open field arena for male Lnx1−/−;Lnx2−/− mice." (PMID 40269869, 2025). "The underlying basis for the distinct anxiety-related and risk-taking behavioural phenotypes of Lnx1−/− and Lnx2−/− mice at the molecular and neural circuitry level are not immediately obvious." (PMID 40269869, 2025). "Both the dark-light emergence and wire beam bridge tasks revealed significant changes in parameters indicative of either decreased anxiety or increased risk-taking for Lnx2−/− and Lnx1−/−;Lnx2−/−, but not Lnx1−/− mice." (PMID 40269869, 2025). "We previously observed decreased anxiety-related behaviour in Lnx1-/-;Lnx2-/- double knockout mice in the elevated plus maze test, which is based on rodents’ preference to explore and spend time in the “safer” environment of the closed, versus the open arms of the maze." (PMID 40269869, 2025). "Knockout LNX1 and LNX2 mice exhibited decreased anxiety-related behavior, though the mechanisms remained unknown." (PMID 33371872, 2020). "We previously reported that mice lacking both LNX1 in the central nervous system and LNX2 globally exhibit decreased anxiety-related behaviour." (PMID 40269869, 2025). "In adult mice, Lnx2 mRNA expression is minimal or absent in key brain regions that control anxiety such as the basolateral amygdala, the bed nucleus of the stria terminalis, the ventral hippocampus or the medial prefrontal cortex." (PMID 40269869, 2025).
Anxiety (continued). "Mice lacking LNX2 as well as the neuronal LNX1p70 and p62 isoforms have recently been shown to exhibit decreased anxiety-related behaviour." (PMID 29121065, 2017). "In agreement with a role for LNX proteins in regulating neural development, double knockout mice lacking both LNX1 and LNX2 in the central nervous system exhibit reduced anxiety-related behaviour." (PMID 29121065, 2017). "The decreased anxiety-related behaviour seen for double knockout animals in the open field and elevated plus maze tests was reproduced and it was found that the absence of both Lnx1 and Lnx2 is required to observe a robust phenotype in these tests." (PMID 40269869, 2025). "Twenty years on from their initial discovery, I discuss here the putative neuronal functions of LNX1/2 proteins in light of the anxiety-related phenotype of double knockout mice lacking LNX1 and LNX2 in the central nervous system (CNS)." (PMID 32714586, 2018).
colorectal cancer (1 paper, 2020). A primary or metastatic malignant neoplasm that affects the colon or rectum. "While the progression of colorectal carcinoma can be regulated by both LNX1 and LNX2, they act in opposing manners." (PMID 33333989, 2020).
dementia (1 paper, 2023). Loss of intellectual abilities interfering with an individual's social and occupational functions. "LNX2 and ALDH2 may be potential genetic markers and new targets for the diagnosis and treatment of MCI and T2DM, which are promising for delaying the occurrence and development of dementia." (PMID 37189611, 2023).
developmental delay (1 paper, 2025). "Thus it is possible that differences in USVs are reflective of differences in body weight and a general developmental delay in Lnx1−/− and Lnx1−/−;Lnx2−/− mice that could, for example, cause altered laryngeal morphology or ability to control breathing with consequent changes in USVs." (PMID 40269869, 2025).
glioma (1 paper, 2018). A benign or malignant brain and spinal cord tumor that arises from glial cells (astrocytes, oligodendrocytes, ependymal cells). "Down-regulation of LNX1 mRNA was noted in gliomas compared with healthy brain tissue, though this might reflect the fact that LNX1 and LNX2 mRNA are expressed predominantly in neurons and as such would be present at lower levels in gliomas that are derived from glia." (PMID 32714586, 2018).
leukemia (1 paper, 2014). A malignant (clonal) hematologic disorder, involving hematopoietic stem cells and characterized by the presence of primitive or atypical myeloid or lymphoid cells in the bone marrow and the blood. "Finally, knockdown of HLA-DRA in THP-1 leukemia cells, LNX2 in BDCM cells, and SMC2 and RIS1 in both THP1 and BDCM cells also desensitized the cells to AraC, results that were also consistent with our association results." (PMID 24483146, 2014).
mastitis (1 paper, 2021). Inflammation of breast tissue during lactation or postpartum due to an obstructed duct or infection. "LNX2 was described earlier in the literature as a mastitis-related gene and a candidate gene for residual body weight gain." (PMID 34654366, 2021).
pancreatic cancer (1 paper, 2023). "Previous reports indicated that Lnx2 knockdown decreased the expression of the Notch target gene, Hes1, in bon-derived macrophages but did not affect the Notch pathway in a pancreatic cancer cell line." (PMID 36674899, 2023).
preeclampsia (1 paper, 2018). Preeclampsia is a hypertensive disorder of pregnancy that is characterized by new-onset hypertension with proteinuria presenting after 20 weeks of gestation, and depending on mild or severe forms may initially present with severe headache, visual disturbances, and hyperreflexia. "Differential expression of LNX2 mRNA expression in placental tissue was found to be associated with preeclampsia in pregnancy, while an epigenome-wide association study identified a CpG site within the LNX2 gene to be hypomethylated in smokers." (PMID 32714586, 2018).
infection (1 paper, 2019). The state of being infected such as from the introduction of a foreign agent such as serum, vaccine, antigenic substance or organism. "To do this, we ablated the expression of LNX2 using a viral knockdown approach in primary neurons that reduced LNX2 mRNA by 80% after 11 days of infection when compared to neurons infected with a scrambled shRNA." (PMID 31628376, 2019).
tumor (1 paper, 2014). "In our analysis from tumor versus “normal” germline samples, expression data demonstrated significant (p≤ 2.0-fold) down-regulation of LNX2 and FGD6 and up-regulation of CRISP1 in LGG." (PMID 25153720, 2014).
LNX2 also shares sentences with these, for which no sentence is quoted: cancer (1 paper); diabetes (1); diffuse large B-cell lymphoma (1); hyperekplexia (1); inflammatory bowel disease (1).